SH3BGRL (SH3 domain binding glutamate rich protein like)
Description:
Appears to function as an adapter protein that bridges proteins together or proteins with mRNAs. May function as a ubiquitin ligase-substrate adapter. Additionally, associates with translating cytoplasmic ribosomes and may promote the expression of specific mRNAs.
Synonyms: MGC117402; HEL-S-115
Tractability: Antibody: UniProt places it where antibodies can reach, with high confidence; its Gene Ontology location is reachable by antibodies, with medium confidence. PROTAC: ubiquitination databases record sites on it; its protein half-life has been measured.
Gene: Protein-coding gene on chromosome X (81,202,005 to 81,298,547, forward strand). Ensembl gene ENSG00000131171.
Subcellular location: Cytoplasm, cytosol; Cell membrane
Subcellular location (Human Protein Atlas): Cytosol
Gene Ontology:
Molecular function: protein-RNA adaptor activity; ubiquitin-like ligase-substrate adaptor activity
Biological process: positive regulation of cytoplasmic translational initiation; proteasome-mediated ubiquitin-dependent protein catabolic process
Cellular component: cytosol; extracellular exosome; extracellular region; plasma membrane; cytoplasm; nucleus
Homologues: Orthologues: chimpanzee SH3BGRL (100% identical), macaque SH3BGRL (100% identical), rabbit SH3BGRL (98% identical), rat Sh3bgrl1 (96% identical), mouse Sh3bgrl (95% identical), zebrafish sh3bgrl (78% identical), tropical clawed frog sh3bgrl (77% identical), guinea pig SH3BGRL (59% identical). Paralogues in human: SH3BGR (63% identical), SH3BGRL2 (60% identical), SH3BGRL3 (33% identical).